IGKV1-33 (immunoglobulin kappa variable 1-33)
Description:
V region of the variable domain of immunoglobulin light chains that participates in the antigen recognition. Immunoglobulins, also known as antibodies, are membrane-bound or secreted glycoproteins produced by B lymphocytes. In the recognition phase of humoral immunity, the membrane-bound immunoglobulins serve as receptors which, upon binding of a specific antigen, trigger the clonal expansion and differentiation of B lymphocytes into immunoglobulins-secreting plasma cells. Secreted immunoglobulins mediate the effector phase of humoral immunity, which results in the elimination of bound antigens. The antigen binding site is formed by the variable domain of one heavy chain, together with that of its associated light chain. Thus, each immunoglobulin has two antigen binding sites with remarkable affinity for a particular antigen. The variable domains are assembled by a process called V-(D)-J rearrangement and can then be subjected to somatic hypermutations which, after exposure to antigen and selection, allow affinity maturation for a particular antigen.
Synonyms: IGKV133; O18
Tractability: Small molecule: it has a high-quality binding pocket. Antibody: UniProt places it where antibodies can reach, with medium confidence; UniProt predicts a signal peptide or a membrane-spanning region; its Gene Ontology location is reachable by antibodies, with medium confidence.
Gene: Immunoglobulin variable (V) gene on chromosome 2 (89,268,001 to 89,268,506, reverse strand). Ensembl gene ENSG00000242076.
Subcellular location: Secreted; Cell membrane
Pathways (Reactome):
Immune System: Antigen activates B Cell Receptor (BCR) leading to generation of second messengers; CD22 mediated BCR regulation; Classical antibody-mediated complement activation; FCERI mediated Ca+2 mobilization; FCERI mediated MAPK activation; FCERI mediated NF-kB activation; FCGR activation; Fc epsilon receptor (FCERI) signaling; Immunoregulatory interactions between a Lymphoid and a non-Lymphoid cell; Initial triggering of complement; Regulation of Complement cascade; Regulation of actin dynamics for phagocytic cup formation; Role of LAT2/NTAL/LAB on calcium mobilization; Role of phospholipids in phagocytosis
Disease: FCGR3A-mediated IL10 synthesis; FCGR3A-mediated phagocytosis; Potential therapeutics for SARS
Hemostasis: Cell surface interactions at the vascular wall
Vesicle-mediated transport: Scavenging of heme from plasma
Gene Ontology:
Molecular function: identical protein binding; antigen binding
Biological process: immune response
Cellular component: blood microparticle; extracellular region; immunoglobulin complex; plasma membrane
Homologues: Paralogues in human: IGKV1D-33 (100% identical), IGKV1-39 (88% identical), IGKV1D-39 (88% identical), IGKV1D-13 (86% identical), IGKV1-27 (85% identical), IGKV1-6 (85% identical), IGKV1-9 (85% identical), IGKV1-12 (84% identical), IGKV1-16 (84% identical), IGKV1-37 (84% identical), IGKV1-5 (84% identical), IGKV1D-37 (84% identical), and 81 more.
Diseases named in the same sentence as IGKV1-33 in open-access papers:
IGKV1-33 is named in the same sentence as 2 diseases in open-access papers, as found by Europe PMC text mining. Sharing a sentence is not in itself a finding about the gene and the disease. The quoted sentences say what the papers report.
AL amyloidosis (2 papers, 2021 to 2023). AL Amyloidosis is a plasma cell disorder characterized by the aggregation and deposition of insoluble amyloid fibrils derived from misfolding of monoclonal immunoglobulin light chains usually produced by a plasma cell tumor. "Immunoglobulin gene IGKV1-33 is specifically expressed in P23 multiple myeloma patients (P = 5.3E-30, one-way analysis of variance), while IGHV4-28 is specifically expressed in P21 multiple myeloma patients (P = 1.8E-12, one-way analysis of variance)." (PMID 37155154, 2023). "Doxycycline also suppressed amyloid deposition in a mouse model of AL amyloidosis and inhibited amyloid formation, but not aggregation, of a full-length LC derived from the IGKV1-33 gene." (PMID 34208058, 2021).
IGKV1-33 also shares sentences with these, for which no sentence is quoted: multiple myeloma (1 paper).